MTOR (mechanistic target of rapamycin kinase)
Diseases named in the same sentence as MTOR in open-access papers (continued):
Sharing a sentence is not in itself a finding about the gene and the disease.
cancer (continued). "For instance, CMV infection increases activation of oncogenic pathways such as PI3K/Akt/mTOR, Wnt, NF-kB, EGFR, ERK, amphiregulin, and SOX-2, increasing cancer cell growth, survival, and metabolism." (PMID 40563634, 2025). "The phosphoinositide 3-kinase (PI3K)/protein kinase B (Akt)/mammalian target of rapamycin (mTOR) signaling, necessary for metabolic reprogramming, is orchestrated by TDEV to abrogate immune response and drive cancer cell proliferation." (PMID 40443670, 2025). "CASC9 was found to activate mTOR-dependent autophagy and EMT pathway activity in CRC to promote cancer progression." (PMID 40746360, 2025). "FGFR signaling plays a pivotal role in cancer biology by activating key pathways such as JAK/STAT, PI3K/AKT/mTOR, and RAS-RAF-MEK-MAPK." (PMID 40393028, 2025). "In State 2, the upregulation of pathways such as antigen presentation, mTOR signaling, and NOD-like receptor signaling suggests that cancer cells in this state are in an active growth and proliferation phase, with inflammatory responses present in the tumor." (PMID 40244296, 2025). "PI3K/Akt activate downstream mammalian target of rapamycin (mTOR) and HIF-1α, promoting angiogenesis, which is important for cancer cell survival in a hypoxic environment." (PMID 40427390, 2025). "Key signaling pathways such as PI3K/Akt, mTOR, and AMPK not only regulate cell survival and proliferation but also directly affect the metabolic status of cancer cells." (PMID 39744225, 2025). "Inhibitory effects for GZMA in cancer were seen mainly in the RTK (19%) pathway, with some inhibitory effects in the Hormone AR (9%), PI3K/AKT (9%), TSC/mTOR (9%), Cell Cycle (6%), and DNA Damage (6%) pathways." (PMID 40002821, 2025). "Various cancer types and cellular pathways, such as PI3K/AKT/mTOR and NF-kB signaling, are depicted." (PMID 41220717, 2025). "Their ability to disrupt cancer pathways—such as PDK1/Akt, MAPK/ERK1/2, and Akt/mTOR—alongside their role in apoptosis induction and angiogenesis inhibition, highlights their therapeutic versatility." (PMID 40718442, 2025). "Flavonoids in YWLS, known for their anti-cancer properties, inhibit tumor proliferation and induce apoptosis by downregulating the PI3K/AKT/mTOR signaling pathway." (PMID 40520175, 2025). "On the other hand, MYC promotes cancer cell proliferation and inhibits apoptosis by regulating multiple components of the PI3K/AKT/mTOR pathway." (PMID 40717965, 2025). "In our study, we found that USP15 can interact with LGALS3 and activate the AKT/mTOR pathway by phosphorylating the AKT and mTOR proteins to exert cancer-promoting functions." (PMID 39794359, 2025). "Commonly dysregulated pathways in endometrioid endometrial cancer, namely the PI3K/AKT/mTOR, MAPK/RAS, Wnt, and PLD signaling pathways, were further investigated to identify the protein expression levels in cancer and control cases." (PMID 41284888, 2025). "Importantly, resistant cancer cells often compensate for MAPK inhibition by activating parallel survival pathways such as PI3K/AKT/mTOR, suggesting that dual inhibition of mTOR and MAPK signaling in combination with L-ASNase could be an effective strategy to prevent resistance." (PMID 41459545, 2025). "Chronic stress and cancer induce a systemic pro‐inflammatory state through common signaling pathways such as NF‐kB, STAT3, and mTOR, promoting tumor growth and metastasis while also contributing to neuroinflammation." (PMID 40387308, 2025). "In cancer cell lines, inhibition of the phosphatidylinositol 3-kinase (PI3K) and the mammalian TOR (mTOR) pathway reduces oxygen consumption by reducing mitochondrial respiration coupled to ATP production." (PMID 41423448, 2025). "These compounds induce cell cycle arrest and apoptosis and target critical cancer pathways, such as PI3K/AKT, mTOR, and FOXO transcription factors, thereby disrupting tumor growth and enhancing tumor sensitivity to therapies." (PMID 40718442, 2025).
cancer (continued). "Over time, during the second stage, the antigen presentation signaling pathway, mTOR signaling pathway, and NOD-like receptor signaling pathway in CNV cancer cells were upregulated, promoting tumor angiogenesis, metabolic reprogramming, and metastasis." (PMID 40244296, 2025). "Transcriptomic and proteomic analysis shows that WAC, mTOR, R2TP, and TTT are co‐expressed across several human cancers, supporting that WAC is part of a functional pathway with mTOR, R2TP, and TTT." (PMID 40653822, 2025). "On the other hand, the “double-edged sword” autophagy that helps the survival of the cancer cells and at the same time induces cell death is regulated by the PI3K/AKT/mTOR pathway." (PMID 38584538, 2025). "Through inhibition of PI3K/Akt/mTOR and MAPK/ERK signaling, quercetin promotes apoptosis and reduces proliferation specifically in cancer cells while sparing healthy cells." (PMID 40084006, 2025). "Even though the result is not statistically significant, the increased trend of phosphorylated mTOR was noted in this study, and the reciprocal correlation between phosphorylated AKT and mTORC1 was also reported in cancer." (PMID 39980332, 2025). "Specifically, the downregulated genes were enriched in pathways involved in cancer, Hippo, Ras, PI3K-AKT, mTOR, focal adhesion, and Wnt signaling." (PMID 41551143, 2025). "Previous studies have shown that the PI3K-Akt-mTOR, JAK-STAT3, and MAPK pathways are downstream of AT1R, which promotes cell proliferation and cancer progression 6,71-73." (PMID 40386053, 2025). "Focusing on significantly enriched pathways like Cyclins and Cell Cycle Regulation and IL‐8 signalling, along with the classical cancer pathways of PI3K/AKT Signalling and mTOR Signalling, we conducted a protein–protein interaction (PPI) network analysis." (PMID 40145254, 2025). "Apart from mTOR, MAPK-interacting kinases (MNK1 and MNK2) perform a role in cancer cell proliferation by influencing the translation process." (PMID 39779613, 2025). "miRNA-21, a molecule potentially suitable as a marker for some cancer types, can augment signaling in the PI3K/AKT/mTOR pathway." (PMID 41373772, 2025). "In Arg-deprived cancer cells, Isp deregulated the PI3K-Akt-mTOR pathway, exacerbated endoplasmic reticulum (ER) stress, and triggered profound caspase-dependent apoptosis." (PMID 41003496, 2025). "Regarding oncogenic signaling pathways with key roles in regulating cancer cell growth, proliferation, survival, and metabolism, including PI3K/AKT, RAS/MAPK, RTK, and TSC/mTOR, a consistent pattern emerged." (PMID 40806276, 2025). "MTV and TLG, measured via PET/CT, are emerging as prognostic markers in HER2+ cancers, reflecting glycolytic activity driven by HER2/PI3K/AKT/mTOR signaling." (PMID 40276059, 2025). "The signaling pathways that play a role in cancer advancement, particularly the PI3K/AKT/mTOR and VEGF pathways, are controlled differently in μg spheroids." (PMID 41516217, 2025). "Related results indicated that the 27 CEDGs were significantly involved in famous cancer-related pathways, including apoptosis, cell cycle, DNA damage, EMT, hormone AR, hormone ER, PI3K/AKT, RTK, RAS/MAPK and TSC/mTOR pathways." (PMID 40478912, 2025). "Autophagy is also considered as a potential therapeutic target in cancer, which can be regulated by PI3K/AKT/mTOR pathway and exerts intricate effects on tumor cells." (PMID 40771929, 2025). "Our findings add to prior research demonstrating thioridazine’s anti-cancer activity through various mechanisms, including PI3K/Akt/mTOR pathway suppression and as a dopamine receptor antagonist." (PMID 40150732, 2025). "Other proteins dysregulated in cancers and required for tumor growth, such as AKT, mTOR, and hypoxia-inducible factors (HIFs), individually promote glycolysis via transcriptional upregulation and phosphorylation of glucose transporters and glycolytic enzymes." (PMID 40734168, 2025).
cancer (continued). "We found MTOR and CAMKK2 as a feature important to both Luminal B and HER2-enriched cancers, while PIK3R4, a regulatory subunit of PI3K complex, was observed to be significant to TNBC and HER2-enriched cancers within the autophagy module." (PMID 40700427, 2025). "According to previous reports, MSI2 can interact with mRNAs and regulate the translation of several oncogenic proteins related to cancer signaling pathways, such as the TGFβ/SMAD, mTOR, PI3K/Akt, cMET, NUMB/Notch, cMyc, and Hh signaling pathways." (PMID 39990676, 2025). "Beyond infectious disease, GBP2 demonstrates a context-dependent dual role in cancer—acting as either a tumor suppressor or an oncogene by modulating key signaling pathways including JAK-STAT, Wnt/β-catenin, and PI3K/AKT/mTOR." (PMID 41181145, 2025). "Therapies, such as dual PI3K/mTOR inhibitors or PI3K inhibitors with controlled FOXO modulation, offer promising avenues to disrupt cancer cell survival mechanisms while minimizing resistance and preserving normal cellular homeostasis." (PMID 40604062, 2025). "We demonstrated that NR6A1 plays an oncogenic role, that it activates p-mTOR, and increases the levels of HK1 in these cancer cells." (PMID 41219936, 2025). "Given the central role of the mTOR/PI3K/Akt signaling axis in regulating autophagy and cancer in general, we examined the effects of these two compounds on the expression of the mTOR pathway regulator GβL/mLST8." (PMID 41155718, 2025). "In hypoxia, HIF1-α also induces the expression of NR2F1-AS1, which positively regulates its neighboring gene NR2F1, to promote cancer cell proliferation, migration and invasion by activating AKT/mTOR signaling." (PMID 39940704, 2025). "IGF‐1 then binds to its IGF‐1R, activating key oncogenic pathways such as PI3K/AKT/mTOR and MAPK/ERK, which drive cell proliferation, survival, and metabolic adaptation in cancer cells." (PMID 40387523, 2025). "For instance, AKT1 and MTOR are core components of the PI3K/AKT/mTOR pathway, a crucial axis in cancer cell survival and metabolism." (PMID 40699833, 2025). "MTF enhances the response to chemotherapy by targeting CSCs in various cancers, potentially through AMPK activation and mTOR suppression." (PMID 39969135, 2025). "Pan-cancer (pan-cancer/NSCLC models; cross-indication) evidence suggests enhanced ICI sensitivity with TSC1/2 alterations, informing mTOR- and ICI-based strategies." (PMID 41154602, 2025). "After 48 h of ADPE treatment, the MDA‐MB‐231 cancer cell line underwent apoptosis as a result of decreased p‐AKT and p‐mTOR levels." (PMID 40717210, 2025). "This dual effect is mediated by changes in nutrient-sensing pathways, such as mTOR and AMPK, which are differentially regulated in cancer and normal cells." (PMID 39940361, 2025). "Simultaneously, the improper activation of PI3K/AKT/mTOR, c-MET, Gal-l and NF-κ B implies higher proliferation activity of the cancer cells, dysregulated autophagy and hinders apoptosis." (PMID 40022036, 2025). "In our study, an increase in mTOR and LC3 fluorescence was observed in both MM cancer cell lines and MM cancer stem cell lines after LIPUS application compared to baseline." (PMID 40561182, 2025). "In particular, the AMPK/MTOR and the canonical AMPK/PI3K/AKT/MTOR cascades were more highlighted in luminal B cancers (by CAMKK2 and MTOR) and in HER2-enriched cancers (by CAMKK2, PIK3R4 and MTOR), respectively." (PMID 40700427, 2025). "mTOR enhances protein translation (via 4E-BP1, S6K) and suppresses autophagy, promoting cancer cell proliferation." (PMID 40667502, 2025). "This study proved that NKILA suppressed autophagy‐related pathways by activating mTOR, decreased CD8+ T cell cytotoxicity, and consequently augmented PD‐L1 signaling that facilitated immune evasion in ICC cells and enhanced cancer progression." (PMID 41498025, 2025).
cancer (continued). "This positive feedback loop between mTOR and HIF‐1 reinforces the metabolic reprogramming necessary for tumor survival, highlighting the interconnectedness of signaling pathways in cancer metabolism." (PMID 39969135, 2025). "The genetic variants described in our study belong to some of the most common key cancer regulatory networks in solid tumors, such as the RAS/RAF/MAPK and PI3K/AKT/mTOR signaling pathways, the DNA damage repair (DDR) pathways, and cell cycle checkpoints." (PMID 39177668, 2025). "Compound 37 exerts a PKM2-mediated effect on cancer metabolism, decreasing PKM2 mRNA and protein expression via mTOR inhibition in HeLa, HepG2 and MCF-7 cells." (PMID 40941984, 2025). "TIAM1 promotes cancer cell proliferation, invasion, and metastasis via multiple pathways, including AKT/mTOR signaling and ERK/STAT3 signaling." (PMID 40228435, 2025). "Pathway enrichment analysis identified several alterations in cancer‐related signaling pathways, such as PI3K, mTOR, AMP‐activated protein kinase (AMPK), and pathways related to apoptosis induction." (PMID 40206206, 2025). "Conversely, mTOR Class I PI3K and AKT activate oncogenes, suppressing autophagy and promoting cancer formation." (PMID 40248706, 2025). "Given the intricate relationship between mTOR and the AKT pathway and their established crosstalk in various cancer types, we were particularly interested in examining the effect of NSP‐B on mTOR activity in T‐ALL cells." (PMID 39542458, 2025). "In gastric cancer cells, berberine induces autophagy inhibition through the regulation of MAPK/mTOR/p70S6K and AKT pathways, leading to the suppression of cancer cell growth both in vitro and in vivo." (PMID 40490812, 2025). "Tumors with high CIN scores showed pronounced signatures of cancer cell proliferation and activated PI3K/AKT/mTOR signaling compared with tumors with low CIN scores." (PMID 40136696, 2025). "In cancers, autophagy can be activated by deregulating the PI3K/Akt/mTOR pathway, permitting tumor cells to survive in environments lacking nutrients." (PMID 40141319, 2025). "One recent study showed the potential effect of sinulariolide on cancer cells and the results showed a significant reduction in the expression of various proteins, such as MMP9, p39MAPK, mTOR, ERK, and inhibited the EMT process in cancerous cells." (PMID 41321380, 2025). "MicroRNA-199a has been shown to directly target B7-H3 mRNA in cancer cells, leading to decreased cell proliferation, migration, and invasiveness by downregulating the B7-H3-activated AKT/mTOR pathway." (PMID 40801642, 2025). "But in addition, we also observed a strong correlation between TELO2 and RAPTOR (in nine out of 10 cancer types), mLST8 (in 10 out of 10 cancer types), mTOR, and RUVBL2 (in five out of 10 cancer types)." (PMID 40653822, 2025). "There is also strong evidence showing the activation of MTOR cascade due to high levels of HER2, which was supported by our findings through several mechanisms and pathways we identified in our HER2 + cancers that target MTOR and change glucose metabolism." (PMID 40700427, 2025). "For example, the original observations with NM5 were performed in the SGR2 and Huh7.5 cell lines, which are highly susceptible to HCV infection, whereas our study was performed in PANC-1 cancer cells, where compound NM5 behaved like a mTOR stimulant." (PMID 41008592, 2025). "Mitochondrial signaling networks integrate metabolic states with cancer progression through key metabolic sensors such as AMPK, mTOR, and Sirtuins, coordinating cellular energy metabolism during malignant transformation." (PMID 40754534, 2025). "Mammalian target of rapamycin (mTOR) and AMP-activated protein kinase (AMPK) negatively regulate tumor suppressor factors, which induces autophagy and suppresses cancer onset." (PMID 40248706, 2025).
cancer (continued). "PI3K/AKT/mTOR signaling pathway activates SREBP1, further modulating SCD1 for higher MUFA biosynthesis and protecting cancer cells from lipid peroxidation and ferroptosis." (PMID 40709184, 2025). "Pharmacological inhibition of PI3K, Akt, and mTOR, at both protein and mRNA levels, reversing EMT and hindering cancer cell proliferation, invasion, and migration." (PMID 40620671, 2025). "Additionally, the regulation of the PI3K/AKT/mTOR signaling pathway, reduction in the expression levels of Bcl-2, mTOR, and P70S6k, as well as the overexpression of pro-apoptotic proteins like Bax, demonstrate the multi-targeted mechanism of securinine in cancer therapy." (PMID 41001039, 2025). "Insulin resistance and hyperinsulinemia in diabetes further drive cancer progression by activating IR and IGF‐1R pathways, particularly the PI3K/AKT/mTOR cascade, which enhances cell proliferation, survival, and angiogenesis." (PMID 40387523, 2025). "ATP-competitive mTOR inhibitors markedly reduce phosphorylated 4E-BP1 and can effectively prevent eIF4E-mediated cap-dependent translation initiation in cancer." (PMID 40563640, 2025). "In silico analysis identified good binding molecules through molecular docking studies, especially stigmasterol having significant Ki values against the cancer receptors such as PI3K, mTOR, and ERβ." (PMID 40475056, 2025). "Essential mediators of cancer progression, such as MAPK/ERK, Wnt/β-catenin, and PI3K/AKT/mTOR pathways, contribute to disease by facilitating cellular proliferation and migration." (PMID 40227591, 2025). "The current study opens the door for examining the role of mTOR in TLT formation and growth in other organs and in the cancer microenvironment where TLTs drive disease, predict response to chemotherapy, or complicate outcomes." (PMID 40496859, 2025). "These interactions activate diverse signaling cascades, including SAPK/JNK, PI3K/Akt/mTOR, and MAPK/ERK pathways, each contributing to distinct aspects of cancer cell survival, immune evasion, stromal activation, and metastatic colonization." (PMID 41479915, 2025). "Inhibition of mTOR (including mTORC1) with drugs like rapamycin in vitro and in vivo leads to tumor growth arrest and regression in HER2/neu-driven cancer models, further supporting the role of mTORC1 downstream of HER2/neu and upstream of SREBP1." (PMID 40427160, 2025). "Targeting cell cycle-regulatory and proto-oncogenic signaling pathways, including Notch, Wnt, NF-κB, Sonic Hedgehog (SHH), ER, PI3K/Akt/mTOR, and HER2, has become an emerging area in cancer research." (PMID 39858015, 2025). "We found that the low-prognostic model score group was positively correlated with many cancer super-pathways, including MYC targets V2, PI3K AKT MTOR signaling, and DNA repair." (PMID 40661777, 2025). "Collectively, the findings from the literature indicate that Methyl rosmarinate affects several pathways that are often dysregulated in cancer, including EGFR/PI3K/AKT/mTOR and MAPK/ERK, as well as the angiogenesis process." (PMID 40136434, 2025). "Ongoing trials are evaluating targeted therapies (e.g., KRAS, PARP, and mTOR inhibitors), immunotherapies (e.g., checkpoint inhibitors, CAR-T cells, and cancer vaccines), and local treatments like IRE, SBRT, and HIFU." (PMID 40282495, 2025). "Specifically, caffeine and its metabolites can inhibit cancer cell proliferation and induce apoptosis by suppressing the PI3K/AKT/mTOR signaling pathway." (PMID 41142631, 2025). "This activation promotes phosphorylation of Akt and mTOR, subsequently enhancing the activity of MMP2, a critical enzyme driving cancer cell invasiveness." (PMID 40333816, 2025).